DNASE1 (deoxyribonuclease 1)
Diseases named in the same sentence as DNASE1 in open-access papers (continued):
Sharing a sentence is not in itself a finding about the gene and the disease.
COVID-19 (16 papers, 2021 to 2025). A disease caused by infection with severe acute respiratory syndrome coronavirus 2. "A pursuit to uncover why circulating DNase levels did not increase in proportion to NETosis during severe or critical COVID-19 led to the hypothesis that genetic variations in DNASE1 and DNASE1L3 genes might be responsible for the deficiency in DNase amount or function." (PMID 38454482, 2024). "Administering DNase can currently be achieved through aerosols, and some clinical trials (NCT04359654, NCT04402970, NCT04541979, NCT04445285) have tested inhaled DNase1 administration in severe COVID-19 patients, with some benefits reported." (PMID 38454482, 2024). "Further studies are necessary to determine the precise contribution of DNases to degrade free DNA and NETs, with specific assessment of DNase1 and DNase1L3 activities in COVID-19 patients with varying disease severity." (PMID 38454482, 2024). "In view of the role of DNASE1 in clearance of NETs, we explored the level of its expression in the patients of COVID-19 with varying illness severity." (PMID 34775962, 2021). "There is significant down-regulation of DNASE1 in the COVID-19 patients, with greater down-regulation in the COVID-19 patients with ARDS." (PMID 34775962, 2021). "Dexamethasone and colchicine—NETs inhibitors—were recommended to lower COVID-19 patient mortality, and DNase1 could degrade NETs to reduce thrombosis in immunothrombotic models, highlighting that NETs might just be a focus of attention for COVID-19 treatment." (PMID 36590587, 2022). "The study revealed that pediatric COVID-19 with impaired NET degradation exhibited elevated levels of G-actin, a natural inhibitor of DNase1, as well as anti-NET antibodies." (PMID 37906560, 2023). "Remarkably, we found lower levels of DNase1 antigen in plasma samples from COVID-19 patients who were hospitalized compared to non-severe outpatients, aligning with the lower amount of functional DNase observed in the same patients." (PMID 38454482, 2024). "The ratios between all three NET markers and DNase1 antigen were also notably higher in the most severe patients, further supporting the idea of an impaired balance between DNase1 protein and NET markers in the most severe COVID-19 patients." (PMID 38454482, 2024). "Collectively, it appeared that circulating DNase1 and DNase1L3 were not sufficiently upregulated to eliminate the NETs formed in severe and critical COVID-19 patients." (PMID 38454482, 2024). "Our investigation extended to understanding why circulating DNase1 and DNase1L3 were not efficiently upregulated during severe and critical COVID-19." (PMID 38454482, 2024).
Autoimmunity (13 papers, 2006 to 2025). The occurrence of an immune reaction against the organism's own cells or tissues. "In order to study the epistatic effects of genes involved in inhibitory signaling and immune complex clearance on autoimmunity, Siglecg deficient mice were crossed either with Dnase1l3 deficient mice or with a newly generated Dnase1 deficient mouse line." (PMID 36969253, 2023). "While serum DNA is primarily digested by Dnase1 and Dnase1L3, Dnase1 cannot rescue autoimmunity arising from Dnase1L3 deficiencies." (PMID 35974043, 2022). "The proband with the P2RY8-L257 variant did not carry other potentially damaging de novo variants or rare variants in genes known to cause monogenic autoimmunity; only a low-frequency heterozygous DNASE1 variant, Q31E, was identified, inherited from her father." (PMID 34889940, 2022). "Although our data suggest that impaired DNase1 activity is pathogenic in SLE, other factors (alone or in combination with DNase1) may lead to accumulation of circulating chromatin and anti-chromatin autoimmunity." (PMID 33746957, 2021). "The fact that down-regulation of Dnase1 in the kidneys appears after initiation of anti-dsDNA antibody production indicates that loss of renal nuclease activity is not responsible for the appearance of anti-chromatin autoimmunity." (PMID 20856893, 2010). "Taken together, these data suggest that Dnase1 deficiency alone is not sufficient to induce autoimmunity against chromatin, but may play a key role in progression of lupus nephritis." (PMID 20856893, 2010). "Accordingly, a total of 60 genetic variants in the DNase 1 gene (DNASE1) inducing abolishment or marked reduction of the DNase I activity could be identified as genetic risk factors for autoimmunity, irrespective of how sparsely they were distributed in the population." (PMID 31541133, 2019). "Following in vivo pharmacodynamic testing to establish dose range and frequency using DKO mice lacking both DNASE1 and DNASE1L3, we tested the efficacy of the lead murine biologic isoform, LBme, on the development of autoimmunity and loss of tolerance to self-DNA in DKO mice." (PMID 38888971, 2024).
lupus nephritis (13 papers, 2006 to 2025). Glomerulonephritis in the context of systemic lupus erythematosus. "Using both morphological and zymographic methods, the current work extends previous data demonstrating an acquired, selective down-regulation of renal Dnase1 gene expression linked to progression towards end-stage lupus nephritis." (PMID 20856893, 2010). "This recent data is indicative of loss of DNase1 serving as a possible factor in the progression of lupus nephritis." (PMID 20856893, 2010). "We recently reported an acquired loss of renal Dnase1 expression linked to transformation from mild to severe membranoproliferative lupus nephritis in (NZBxNZW)F1 mice." (PMID 20856893, 2010). "Preliminary results from analyses of kidney biopsies from patients with human lupus nephritis demonstrate a similar relationship between severe nephritis and loss of the Dnase1 enzyme (studies in progress)." (PMID 20041189, 2009). "The basic hypothesis motivating the present study was that clinical lupus nephritis is a distinct organ disease with an aetiology linked to an acquired loss of renal Dnase1 enzyme activity." (PMID 20041189, 2009). "Results from Dnase1 staining of additional biopsies from patients with lupus nephritis revealed a similar relationship between Dnase1 staining intensity and the glomerular loci for chromatin-IgG complex deposits." (PMID 20856893, 2010). "In this study we analyzed if loss of renal Dnase1 correlated with increased MMP activity in the kidneys, and with exposure of large chromatin fragments at loci typical for lupus nephritis–namely in the mesangial matrix and in the GBM." (PMID 20041189, 2009). "In a recent study, we demonstrated that the appearance of anti-dsDNA antibodies in (NZBxNZW)F1 (B/W) mice coincided with early signs of development of mesangial nephritis, while reduced renal Dnase1 mRNA expression correlated with progression of lupus nephritis into end-stage organ disease." (PMID 20856893, 2010). "As this may represent a basic mechanism in the progression of lupus nephritis, several aspects of Dnase1 expression in lupus nephritis were analyzed." (PMID 20856893, 2010). "Reduced serum Dnase1 activity was observed in both mesangial and end-stage lupus nephritis." (PMID 20856893, 2010). "In the present study we determined the impact of antibodies to dsDNA, renal Dnase1 and matrix metalloprotease (MMP) mRNA levels and enzyme activities on early and late events in murine lupus nephritis." (PMID 20041189, 2009).
gastric cancer (9 papers, 2021 to 2025). A primary or metastatic malignant neoplasm involving the stomach. "For the DNASE1 1*2 polymorphism, subjects with the genotype GG were significantly linked with gastric cancer (p < 0.001)." (PMID 35996518, 2022). "Genotype and allelic frequencies of the DNASE1 polymorphism in gastric cancer patients and the healthy controls." (PMID 35996518, 2022). "We hypothesized that both polymorphisms in DNASE1 are linked with gastric cancer, by virtue of roles in apoptosis." (PMID 35996518, 2022). "Interestingly, a combination of the HumDN1 and DNASE1 1*2 polymorphisms analysis revealed an increased link of gastric cancer with GG-2/3 genotype (p = 0.008)." (PMID 35996518, 2022). "We hypothesized an association of two polymorphic sites in the exon 8 and the intron 4 of the DNASE1 gene with the risk of gastric cancer." (PMID 35996518, 2022). "Transwell invasion assays showed enhanced invasive capacity of gastric cancer cells treated with NETs, which was reversed by DNase‐1 treatment." (PMID 40059806, 2025). "Compared with the control group, intraperitoneal injection of DNAse-1 reduced the growth volume of the subcutaneous gastric cancer tumors." (PMID 36172371, 2022). "After finding that NETs could promote EMT in gastric cancer, we used DNase‐1 to further validate this experimental result." (PMID 40059806, 2025). "Considering the role of DNase I enzyme in the apoptosis and the effects of genetic polymorphism on its activity, we hypothesized links between the A2317G polymorphism and the 56-bp VNTR (HumDN1) in DNASE1, and gastric cancer." (PMID 35996518, 2022). "In gastric cancer, FEN1, APE1, XPF/XPG, MRN complex, and DNase1 are typically found." (PMID 39000483, 2024).
autoimmune disease (7 papers, 2019 to 2025). A disorder resulting from loss of function or tissue destruction of an organ or multiple organs, arising from humoral or cellular immune responses of the individual to their own tissue constituents. "Studying the expression of DNASE1 in cancer is crucial for understanding cancer pathways, and disturbances in DNASE1 can contribute to autoimmune diseases, potentially increasing the risk of developing cancer." (PMID 38618458, 2024). "DNASE1 has been linked to several diseases, including cancer and autoimmune disorders." (PMID 38618458, 2024). "Deoxyribonuclease-1 (DNASE1) is a ubiquitous endonuclease which degrades the majority of circulating free DNA released from apoptosis and necrotic cell death, with DNASE1 deficiency being previously reported to be associated with autoimmune disease in animal models and humans." (PMID 37474963, 2023). "In this context, our data suggest that recombinant DNase1 may be an attractive therapeutic strategy to lower autoimmune response and disease progression in patients with autoimmune disorders associated with concomitant hypercholesterolemia." (PMID 36098213, 2022). "In conclusion, our studies suggest that enhancing the plasma activity of DNASE1 and DNASE1L3 with our bioavailable enzyme biologic is likely to carry significant therapeutic benefit in patients with autoimmune disease associated with impaired DNASE1L3 activity." (PMID 38888971, 2024). "Likewise, Deoxyribonuclease 1 (DNase1) has been shown to safely degrade NETs across various murine models, including breast cancer, pulmonary inflammation, and autoimmune diseases, with no significant toxicity reported in non-cancer clinical use." (PMID 40805288, 2025).
glomerulonephritis (7 papers, 2006 to 2025). A renal disorder characterized by damage in the glomeruli. "In conclusion, both Dnase1-/- x Siglecg-/-, as well as Dnase1l3-/- x Siglecg-/- aging mice developed glomerulonephritis, with a more severe disease score detected in the latter mouse line." (PMID 36969253, 2023). "Histological analysis of the kidneys revealed glomerulonephritis in both Siglecg-/- x Dnase1-/- and Siglecg-/- x Dnase1l3-/- mice, but with a stronger glomerular damage in the latter." (PMID 36969253, 2023). "In terms of DNase I deficiency, mice deficient in DNASE1 develop ANA and glomerulonephritis." (PMID 38914753, 2024). "Additionally, Dnase1-/- mice were shown to develop SLE-like disease with increased titers of ANAs and prevalence of glomerulonephritis." (PMID 36969253, 2023).
ischemic stroke (7 papers, 2022 to 2025). A stroke disorder caused by obstruction of blood flow to the brain, due to thrombotic (local blood clot formation) or embolic (due to a blood clot or other material traveling from another site) event. "Accordingly, DNase1-mediated reversal of microglia activation, cerebrovascular protection and anti-hemorrhagic effects after ischemic stroke were abolished by co-administration of the cGAS product cGAMP, whereas cGAS deficiency rescued t-PA-associated BBB disruption and cerebral hemorrhage." (PMID 37550658, 2023). "Together with the combined application of DNase1/t-PA, as described in this article, nNIF and related peptides may serve as new therapeutic regimen towards NETs as targets in ischemic stroke." (PMID 37550658, 2023). "Furthermore, treatment of blood clots obtained from ischemic stroke patients with DNase1 ex vivo substantially increased t-PA-induced thrombolysis in comparison to t-PA alone." (PMID 37550658, 2023).
Stroke (7 papers, 2022 to 2025). Sudden impairment of blood flow to a part of the brain due to occlusion or rupture of an artery to the brain. "We developed an innovative conjugate of stroke‐homing peptide (SHp) and DNase1 (SHp‐DNase1) to enhance the stability of DNase in the bloodstream while selectively targeting NETs in thromboembolic events." (PMID 40001309, 2025). "Stroke Homing peptide (SHp)-guided deoxyribonuclease 1 (DNase1) and inhibition of myeloperoxidase (MPO) or peptidyl arginine deiminase-4 (PAD4) can reduce chemotherapy-induced mechanical hyperalgesia and prevent the development of CIPN in mice model." (PMID 39202733, 2024). "Treatment with recombinant human DNase1 allowed for the recanalization of occluded vessels and improved prognosis in murine stroke models, motivating therapeutic use of DNase mutants for thromboprotection." (PMID 37287977, 2023). "Furthermore, clinical trials evaluating a combination of DNAse-1 and tPA as stroke therapy vs. conventional tPA alone are needed to confirm the utility of NETs as therapeutic targets in stroke." (PMID 36082273, 2022). "In our recent study, we found that a stroke‐homing peptide (SHp; CLEVSRKNC) coupled with DNase1 would specifically anchor at the site of microcirculatory ischemia in the lower limbs, effectively alleviating mechanical hyperalgesia." (PMID 40001309, 2025). "Other than accelerating NET degradation via DNAse-1, inhibiting NET formation by targeting PAD4 is a feasible strategy: PAD4 overexpression impairs revascularization and vascular remodeling in stroke, while PAD4 inhibition restores angiogenesis." (PMID 36082273, 2022). "The aim of this study was to test whether deoxyribonuclease 1 (DNase 1) infusion, which cleaves extracellular DNA, could reduce DMT in a transient middle cerebral artery (MCA) occlusion stroke model in rats." (PMID 41229673, 2025).
colorectal cancer (6 papers, 2020 to 2025). A primary or metastatic malignant neoplasm that affects the colon or rectum. "A previous study observed a link between DNASE1 and thrombophilia by degrading neutrophil extracellular traps (NETs) in colorectal cancer, which could potentially lead to cancer-related coagulation problems." (PMID 38618458, 2024). "The study of different phenotypes of DNase I showed that the phenotype 2, with DNASE1*2 polymorphism, may potentially be a good predictor of the development of gastric and colorectal carcinoma, while no such association was found with other types of cancer." (PMID 32664541, 2020).
nephritis (5 papers, 2009 to 2023). Inflammation of renal tissue. "We have recently demonstrated that reduced fragmentation of chromatin during evolution of nephritis concur with an acquired loss of renal Dnase1 mRNA at the time when nephritis transforms into end-stage organ disease." (PMID 20041189, 2009). "The data revealed a dramatic decrease in Dnase1 immunostaining only in renal sections from the patient with severe nephritis." (PMID 20856893, 2010). "Acquired deficiency of renal Dnase1 activity is assumed to promote a progressive exposure of secondary necrotic chromatin in GBM, and a consequent development of severe nephritis." (PMID 20041189, 2009). "BW mice were sacrificed approximately every second week (in sets of 3) until development of end-stage lupus-like nephritis, and were analyzed for renal Dnase1, MMP2 and MMP9 mRNA levels and for corresponding enzyme activities." (PMID 20041189, 2009). "In the other mouse line with a Dnase1 mutation without affecting Trap1, a rather mild increase of autoantibodies and nephritis score is reported from 9 months onwards." (PMID 36969253, 2023). "Further genes were annotated with nephritis (Cndp2, Dnase1 and Scd1)." (PMID 25409434, 2014). "For each parameter, it was difficult to determine correlation between e.g. Dnase1, MMP2 or MMP9 mRNA levels with age in individual mice since nephritis developed at different time points in different mice." (PMID 20041189, 2009). "Since nephritis does not appear at the same age in individual BW mice, instead of relating data to age, levels of Dnase1, MMP2 and MMP9 mRNA were combined for each mouse, and this set of data was sorted by descending Dnase1 mRNA levels." (PMID 20041189, 2009).
bladder cancer (4 papers, 2022 to 2025). "DNASE1 mRNA expression is higher in tumoral tissues of bladder cancer than in the surrounding normal tissues." (PMID 38618458, 2024). "Additionally, the Cancer Genome Atlas (TCGA) data demonstrated that DNASE1 mRNA levels were elevated in bladder cancer tumoral tissues as compared to surrounding normal tissues." (PMID 35793278, 2022). "Thus, it was hypothesized that an increase in DNASE1 activity in bladder cancer tumoral tissues would result in a reduction in ucfDNA molecules produced from DHSs." (PMID 35793278, 2022).
ischemia (3 papers, 2018 to 2025). A hypoperfusion of the BLOOD through an organ or tissue caused by a PATHOLOGIC CONSTRICTION or obstruction of its BLOOD VESSELS, or an absence of BLOOD CIRCULATION. "To achieve targeted delivery of DNase1 to sites of ischemia caused by NETs, we designed the SHp‐DNase1 recombinant protein." (PMID 40001309, 2025). "Our research focus on exploring the effect of short time administration of DNAse-1 on rats after 1 h of ischemia and 2 h of reperfusion." (PMID 30542063, 2018).
lung injury (3 papers, 2016 to 2022). "In this sense, studies targeting platelet activation with either aspirin, a glycoprotein IIb/IIIa inhibitor, or a histone blocking antibody and DNase1 decreased NETs formation and lung injury in an experimental transfusion-related acute lung injury model." (PMID 35811684, 2022). "It has been shown that Dnase1 treatment protected mice from acute lung injury (ALI) whereas Dnase1 KO mice had worse ALI18." (PMID 33731726, 2021).
pneumonia (3 papers, 2021 to 2025). An acute, acute and chronic, or chronic inflammation focally or diffusely affecting the lung parenchyma, caused by an infection in one or both of the lungs (by bacteria, viruses, fungi, or mycoplasma.). "In conclusion, we discover that NETosis is critical in SCAP and highlight H4C15, H3-5, DNASE1, and PRKCB as promising therapeutic targets for severe pneumonia." (PMID 36466920, 2022).
Alzheimer disease (2 papers, 2016 to 2024). A progressive, neurodegenerative disease characterized by loss of function and death of nerve cells in several areas of the brain leading to loss of cognitive function such as memory and language. "In addition, DNase, a commonly used NETs inhibitor, has been successfully applied in the treatment of Alzheimer’s disease, and genetic variants in DNase genes including DNASE1, DNASE2 and DNASE1L3 can result in the downregulation of DNase expression in Alzheimer’s disease." (PMID 38188146, 2024).
breast invasive carcinoma (2 papers, 2020 to 2024). "DNASE1, FUNDC2, and IDS are genes hypermethylated in invasive breast cancer stage, although they demonstrate detectable hypomethylation in ADH and DCIS stages." (PMID 32051475, 2020).